TCAF2C (TRPM8 channel associated factor 2C)
Gene: Protein-coding gene on chromosome 7 (143,639,230 to 143,647,646, reverse strand). Ensembl gene ENSG00000283528.
Gene Ontology:
Molecular function: transmembrane transporter binding
Biological process: negative regulation of anion channel activity; positive regulation of protein targeting to membrane; regulation of monoatomic anion transmembrane transport
Cellular component: cell junction; plasma membrane
Homologues: Orthologues: chimpanzee TCAF2 (98% identical), macaque TCAF2 (96% identical), dog TCAF2 (80% identical), mouse Tcaf2 (74% identical), rat Tcaf2c (73% identical), tropical clawed frog tcaf1 (47% identical), zebrafish si:ch211-210b2.4 (41% identical), zebrafish si:ch211-210b2.3 (41% identical), zebrafish zgc:162193 (41% identical), zebrafish si:ch211-210b2.2 (40% identical). Paralogues in human: TCAF2 (99% identical), TCAF1 (63% identical).